RFXAP (regulatory factor X associated protein)
Description:
Part of the RFX complex that binds to the X-box of MHC II promoters.
Synonyms: MHC2D4
Tractability: PROTAC: UniProt records ubiquitination sites on it; ubiquitination databases record sites on it; its protein half-life has been measured.
Gene: Protein-coding gene on chromosome 13 (36,819,222 to 36,829,104, forward strand). Ensembl gene ENSG00000133111.
Subcellular location: Nucleus
Subcellular location (Human Protein Atlas): Nuclear speckles
Gene Ontology:
Molecular function: DNA-binding transcription activator activity, RNA polymerase II-specific; protein binding; RNA polymerase II transcription regulatory region sequence-specific DNA binding; DNA binding
Biological process: positive regulation of transcription by RNA polymerase II; positive regulation of MHC class II biosynthetic process; regulation of transcription by RNA polymerase II
Cellular component: nuclear speck; nucleus; RNA polymerase II transcription regulator complex
Genetic constraint (gnomAD): Loss-of-function variants: 15 observed, 15.86 expected, observed/expected ratio (o/e) 0.95, 90% interval 0.63 to 1.45. The synonymous counts are far from expectation, so gnomAD's model fits this gene poorly and the ratio says little. Missense variants: 308 observed, 277.17 expected, observed/expected ratio (o/e) 1.11, 90% interval 1.01 to 1.22. Synonymous variants: 152 observed, 115.72 expected, observed/expected ratio (o/e) 1.31, 90% interval 1.15 to 1.5.
Gene-disease validity (ClinGen):
ClinGen rates the evidence that RFXAP causes each of these diseases.
MHC class II deficiency (autosomal recessive): Definitive. Immunodeficiency by defective expression of HLA class 2 is a rare primary genetic immunodeficiency disorder characterized by partial or complete absence of human leukocyte antigen class 2 expression resulting in severe defect in both cellular and humoral immune response to antigens.
Homologues: Orthologues: chimpanzee RFXAP (99% identical), macaque RFXAP (98% identical), guinea pig RFXAP (80% identical), rabbit RFXAP (73% identical), mouse Rfxap (66% identical), rat Rfxap (66% identical), tropical clawed frog rfxap (42% identical), zebrafish rfxap (35% identical).
Diseases named in the same sentence as RFXAP in open-access papers:
RFXAP is named in the same sentence as 10 diseases in open-access papers, as found by Europe PMC text mining. Sharing a sentence is not in itself a finding about the gene and the disease. The quoted sentences say what the papers report.
pancreatic cancer (24 papers, 2015 to 2023). "Pancreatic cancer-derived sEVs inhibit the expression of regulatory factor X-associated protein(RFXAP) through miR-212-3p, thereby reducing the expression of MHC II, inducing immune tolerance of dendritic cells, and inhibiting the immune response." (PMID 34980146, 2022). "Pancreatic tumor-derived exosomal miR-212-3p inhibits MHC-II by downregulating the expression of regulatory factor X-associated protein (RFXAP), which promotes the immune tolerance of DCs." (PMID 35562884, 2022). "Exosomes derived from pancreatic cancer (PaCa) cells had high levels of miR-212-3p, which inhibited the expression of regulatory factor X-associated protein (RFXAP), resulting in a decrease in the expression of MHC II molecules and inducing immune tolerance." (PMID 35571530, 2022). "For example, in pancreatic cancer, it has been observed that MHC II transcription factor regulatory factor X-associated protein (RFXAP) was inhibited by miR-212-3 transferred from pancreatic cancer-secreted exosomes." (PMID 34205256, 2021). "Pancreatic cancer (PC) -derived exosomal miR-212-3p can be transferred to DC to inhibit the expression of regulatory factor X-associated protein (RFXAP), which subsequently leads to a decline in MHC II expression in DC, thereby inducing immune tolerance in DC." (PMID 34084160, 2021). "These pancreatic cancer-derived exosomes inhibit the expression of regulatory factor X associated protein (RFXAP), an important transcription factor for MHC II, in dendritic cells (DCs), to induce immune tolerance." (PMID 31795140, 2019). "and co-workers demonstrated that exosomal miRNA-212-3p from pancreatic cancer cells degrades Regulatory factor X-associated protein (RFXAP) mRNAs in DCs, leading to immune tolerance through minimizing of MHC II molecules." (PMID 31291956, 2019). "Similarly, EVs enriched from pancreatic cancer cells contain miR-212-3p which, transferred by DCs, downregulates the expression of regulatory factor X-associated protein (RFXAP)." (PMID 36498469, 2022). "Furthermore, pancreatic cancer-associated exosomes shuttle miR-212-3p to inhibit regulatory factor X-associated protein (RFXAP), a regulatory transcription factor for the MHC-II gene, and initiate immune tolerance in dendritic cells (DCs)." (PMID 32121073, 2020). "MiR-212-3p was also found expressed in pancreatic cancer-derived exosomes, inhibiting the expression of the regulatory factor X-associated protein (RFXAP) and consequently decreasing major histocompatibility complex (MHC) class II expression when released into DCs." (PMID 30699928, 2019). "Moreover, pancreatic cancer-derived exosomes transfer miRNAs toDCs and inhibit Regulatory factor X-associated protein(RFXAP) expression via miR-212-3p, inducing MHC II downregulation and immune tolerance of DCs." (PMID 30309355, 2018). "Therefore, further studies on RFXAP deficiency in pancreatic cancer may help to find molecular markers related to metastasis and new targets for gene therapy." (PMID 26337469, 2015). "MiR-212-3p is also overexpressed in pancreatic cancer-derived exosomes, which make DCs unable to activate CD4+ T cells by inhibiting the expression of the regulatory factor X-associated protein (RFXAP) and consequently decreasing MHC II expression." (PMID 35501802, 2022). "Immunohistochemistry was used to detect the expression of RFXAP in tissue samples, which showed that the RFXAP-positivity rate was significantly lower in pancreatic cancer samples than in the control group [37.0% (17/46) vs. 65.0% (13/20); P < 0.05]." (PMID 33093461, 2020). "RFXAP expression was significantly lower in the pancreatic cancer-cell lines than in HPDE6-C7 cells." (PMID 33093461, 2020). "In this study, we found that the expression of RFXAP was relatively low in pancreatic cancer, and its downregulation was correlated with tumor stage and poor prognosis." (PMID 33093461, 2020).
pancreatic cancer (continued). "We used qRT-PCR to determine the mRNA levels of RFXAP in four pancreatic cancer-cell lines (BxPC-3, MiaPACA-2, HPC-Y5, and PANC-1) and one normal pancreatic ductal epithelial cell line (HPDE6-C7)." (PMID 33093461, 2020). "EV-miR-212-3p from pancreatic cancer cells decreases MHC II transcription factor RFXAP expression of dendritic cells by targeting RFXAP, leading to reduced MHC II expression and potential immune tolerance." (PMID 32503543, 2020). "The results validated that pancreatic cancer derived exosomal miR-212-3p would inhibit RFXAP and MHC II expression in iDC." (PMID 26337469, 2015). "By the Pearson correlation test, it was validated that miR-212-3p was significantly negatively correlated with RFXAP in pancreatic cancer (r = −0.864, P < 0.01)." (PMID 26337469, 2015). "The regulatory factor-X-associated protein (RFXAP), a key transcription factor for the MHC-II gene, is downregulated by pancreatic cancer-secreted exosomes containing miRNA-212-3p, leading to the inhibition of MHC class II expression and CD4+ T-cell inactivation." (PMID 33396739, 2020). "Additionally, pancreatic cancer-derived exosomes are also known to transfer microRNAs to dendritic cells and inhibit RFXAP expression via miR-212-3p23." (PMID 30237397, 2018). "The expression of regulatory factor X-associated protein (RFXAP) and major histocompatibility complex class II (MHC classII), which contribute to immune tolerance, has been observed to be suppressed in dendritic cells by miR-212-3p transported in exosomes released by pancreatic cancer cells." (PMID 31533332, 2019). "In the current study, RFXAP expression was significantly lower in pancreatic cancer-cell lines and tumor tissues than in the corresponding controls, and negative RFXAP expression was significantly correlated with TNM stage, T stage, and prognosis." (PMID 33093461, 2020).
bare lymphocyte syndrome (6 papers, 2012 to 2025). "Regulatory factor X-associated protein (RFXAP) is a key transcription factor for the MHC II gene whose deficiency can lead to a rare severe immunodeficiency disorder termed bare lymphocyte syndrome." (PMID 28231804, 2017). "Major histocompatibility complex class II (MHC II) deficiency (bare lymphocyte syndrome type II) is an autosomal-recessive combined immunodeficiency caused by pathogenic variants in the transcriptional regulators CIITA, RFXANK, RFX5, or RFXAP." (PMID 41376631, 2025). "RFXAP is a transcription factor for MHC II, and its deficiency leads to bare lymphocyte syndrome, a rare severe immunodeficiency disease caused by MHC II dysfunction." (PMID 26337469, 2015). "Regulatory factor X-associated protein (RFXAP) is a key transcription factor for the MHC II gene, and its deficiency can lead to a rare severe immunodeficiency disorder termed bare lymphocyte syndrome." (PMID 26337469, 2015). "We also measured MHCI mRNA expression by quantitative real-time RT-PCR (qRT-PCR) in in vitro-generated B cell mutants and B cell lines derived from bare lymphocyte syndrome (BLS) patients carrying inactivating mutations in CIITA, RFX5, RFXAP, and RFXANK." (PMID 25811463, 2015).
Immunodeficiency (5 papers, 2015 to 2021). Failure of the immune system to protect the body adequately from infection, due to the absence or insufficiency of some component process or substance. "For example, in subclusters of osteo-like, basal/stromal, and endothelial cells, regulatory factor X (RFX5, RFXAP, and RFXANK) can mediate their immunodeficiency function by binding domains of RFX- and NFX-." (PMID 35237614, 2021).
combined immunodeficiency (3 papers, 2012 to 2025). A broad classification of inherited disorders presenting at birth that affect both the cell-mediated and humoral aspects of the immune response. "Genetic studies of patients with combined immunodeficiency (CID) with predominant CD4 cell deficiency have revealed mutations in genes encoding regulatory factors of the expression of MHC class II molecules such as CIITA, RFXANK, RFX5 or RFXAP." (PMID 25205547, 2014).
colorectal cancer (1 paper, 2010). A primary or metastatic malignant neoplasm that affects the colon or rectum. "Ten of these genes (WDR67, RFXAP, RP11-50D16.3, CAB39L, THSD1, SPRY2, TGDS, CLDN10, SLC10A2, CD33L3) have been reported changed in tumor tissues, while only 2 (RP11-50D16.3, SLC10A2) have been reported to appear changed in colorectal cancer." (PMID 20467480, 2010).
lymphopenia (1 paper, 2019). Reduction in the number of lymphocytes. "Isolated CD4 lymphopenia has been described with MHC Class II deficiency (RFXANK, CIITA, RFXAP) and hypomorphic RAG variants." (PMID 31572360, 2019).
tumor (9 papers, 2010 to 2023). "In another study, tumor-derived exosomal miRNA-212-3p was found to inhibit the expression of RFX-associated protein (RFXAP), which decreased the expression of major histocompatibility complex class II (MHC II) and mediated the immune tolerance of DCs." (PMID 34243775, 2021). "However, few studies have investigated the role of RFXAP deficiency in tumor progression." (PMID 26337469, 2015). "Low levels of MHC-II are associated with poor prognosis and histological grade, potentially due to dysfunctionalities in the RFX protein complex containing RFXAP, promoting tumor immune tolerance and invasion." (PMID 34207163, 2021). "The MeRIP-qPCR and WB results showed that although the m6A methylation levels of KHDRBS2 and RFXAP were both increased in tumor tissues, the protein expression levels of KHDRBS2 was decreased, while RFXAP protein expression was unchanged." (PMID 34422827, 2021). "RFXAP (regulatory factor X-associated protein) is a critical transcription factor for MHC II molecules and may also bind other tumor suppressor proteins." (PMID 34422827, 2021). "A comprehensive analysis of PDA tumor cells-derived EVs miRNA and EVs-treated DC mRNA expression profiles led to the identification of the transcription factor of MHC-II, regulatory factor X-associated protein (RFXAP), inhibited in PDA by EV-derived miR-212-3p." (PMID 34207163, 2021). "However, the mechanisms have not yet been fully elucidated, and deficiency of RFXAP in tumor progression has not been reported previously." (PMID 26337469, 2015). "We revealed that RFXAP expression was relatively low in PDAC and correlated with tumor stage and poor prognosis." (PMID 33093461, 2020). "We further verified the expressions of RFXAP and KHDRBS2 mRNAs in 19 LUAD patients, the results showed that RFXAP and KHDRBS2 expressions in tumor tissues were lower than that in matched normal adjacent lung tissues, which were consistent with that of GEPIA database." (PMID 34422827, 2021).
cancer (6 papers, 2018 to 2025). A tumor composed of atypical neoplastic, often pleomorphic cells that invade other tissues. "Together these results indicate that fisetin inhibits cancer-cell proliferation by inducing DNA damage via RFXAP/KDM4A-dependent demethylation of histone H3K36, which might be a novel therapeutic target for PDAC." (PMID 33093461, 2020). "The regulation of these genes’ expression by RFXANK, RFXAP, and RFX5 TFs has been pointed across 18 different cancer types." (PMID 40226614, 2025). "Other important positive biomarkers shared across all 18 cancer types were RFXANK, RFXAP, and RFX5, which form the RFX trimeric complex." (PMID 34430923, 2021). "However, the role of RFXAP deficiency in malignant tumors has not been documented." (PMID 33093461, 2020). "Additionally, 46 out of the 49 TFs are known to play roles in CRC and the remaining three (RFXAP, SPI1 and RFX5) are related to other cancers." (PMID 36760999, 2023).
RFXAP also shares sentences with these, for which no sentence is quoted: lymphoid cancers (1 paper); pancreatic adenocarcinoma (1).